MSANTD3 (Myb/SANT DNA binding domain containing 3)
Synonyms: C9orf30; L8; MGC17337
Tractability: PROTAC: UniProt records ubiquitination sites on it; its protein half-life has been measured.
Gene: Protein-coding gene on chromosome 9 (100,426,693 to 100,451,734, forward strand). Ensembl gene ENSG00000066697.
Subcellular location (Human Protein Atlas): Nucleoplasm; Cytosol; Nuclear bodies
Gene Ontology:
Molecular function: protein binding
Genetic constraint (gnomAD): Loss-of-function variants: 11 observed, 28.04 expected, observed/expected ratio (o/e) 0.39, 90% interval 0.25 to 0.65. The upper end of that interval is the gene's LOEUF score, 0.65, which puts it in group 2 of 6, group 1 being the genes least tolerant of losing a copy. Missense variants: 250 observed, 352.48 expected, observed/expected ratio (o/e) 0.71, 90% interval 0.64 to 0.79. Synonymous variants: 131 observed, 132.82 expected, observed/expected ratio (o/e) 0.99, 90% interval 0.86 to 1.14.
Homologues: Orthologues: pig MSANTD3 (99% identical), rat Msantd3 (97% identical), mouse Msantd3 (96% identical), tropical clawed frog msantd3 (74% identical).
Diseases named in the same sentence as MSANTD3 in open-access papers:
MSANTD3 is named in the same sentence as 12 diseases in open-access papers, as found by Europe PMC text mining. Sharing a sentence is not in itself a finding about the gene and the disease. The quoted sentences say what the papers report.
salivary gland acinic cell carcinoma (3 papers, 2017 to 2025). A carcinoma of the salivary gland characterized by serous acinar cell differentiation. "Nevertheless, one study linked MSANTD3 to salivary gland acinic cell carcinoma." (PMID 39862296, 2025). "MSANTD3 is an oncogene in salivary gland acinic cell carcinoma." (PMID 30704450, 2019).
adenoid cystic carcinoma (2 papers, 2017 to 2020). A malignant tumor arising from the epithelial cells. "Although the exact role(s) of MSANTD3 in AcCC oncogenesis remain to be determined, it is also intriguing that MYB itself, which of course also harbors a Myb/SANT-like domain, is part of a gene fusion that characterizes a different salivary gland tumor: MYB-NFIB in adenoid cystic carcinoma." (PMID 28212443, 2017).
adenosquamous carcinoma (1 paper, 2017). A carcinoma composed of malignant glandular cells and malignant squamous cells. "While 51% of salivary specimens (benign and malignant) tested were void of any MSANTD3 staining, strong MSANTD3 expression was observed in a substantial subset of mucoepidermoid carcinomas (5/25, 20%) and adenosquamous carcinomas (3/5, 60%)." (PMID 28212443, 2017).
brain tumors (1 paper, 2014). "MSANTD3 is a Myb/SANT-like DNA-binding domain containing protein and is associated with brain tumors." (PMID 24743307, 2014).
cardiomyopathy (1 paper, 2021). A disease of the heart muscle or myocardium proper. "The candidate gene MSANTD3 was included in the module ‘midnight blue’ (r = 0.12, p < 0.05), in which the KEGG pathways related to cardiomyopathy, and the GO terms related to muscle such as muscle tissue development and muscle contraction, were over-represented." (PMID 34399688, 2021).
salivary gland cancer (1 paper, 2017). A primary or metastatic malignant neoplasm that affects the major or minor salivary glands. "MSANTD3 displayed heterogeneous expression in normal salivary ductal epithelium, as well as among other histologic types of salivary gland cancer though without evidence of translocation." (PMID 28212443, 2017).
cancer (1 paper, 2017). A tumor composed of atypical neoplastic, often pleomorphic cells that invade other tissues. "Analysis of publicly-available The Cancer Genome Atlas (TCGA) RNA-seq data also showed varied MSANTD3 transcript levels across cancer types, with several exhibiting significantly higher expression in cancer compared to matched normal tissue." (PMID 28212443, 2017). "Furthermore, in a cell line model, MSANTD3 overexpression led to the upregulation of genes involved in protein synthesis, a cellular process often upregulated in cancer." (PMID 28212443, 2017).
neoplasias (1 paper, 2017). "Beyond the salivary gland, MSANTD3 was expressed in a small subset of normal cell types and in many neoplasms." (PMID 28212443, 2017). "A hitherto unstudied gene, we also here surveyed MSANTD3 expression across a diverse set of human tissues and neoplasias, and carried out preliminary studies of its function." (PMID 28212443, 2017).
MSANTD3 also shares sentences with these, for which no sentence is quoted: Acinic cell carcinoma (2 papers); salivary gland tumor (2); bladder transitional cell carcinoma (1); mucoepidermoid carcinoma (1).